MTOR (mechanistic target of rapamycin kinase)
Diseases named in the same sentence as MTOR in open-access papers (continued):
Sharing a sentence is not in itself a finding about the gene and the disease.
infection (continued). "An increased expression of CTLA-4 during the acute phase of infection may block mTOR activation, thus preventing protein translation, (including Otub-1) and leading to the maintenance of GRAIL expression with reduced T cell proliferation and cytokine production." (PMID 28114324, 2017). "However, the Dot/Icm apparatus itself did not trigger this cell death response because infections with L. dumoffii, which encodes a homologous Dot/Icm system, did not induce host cell death in Myd88-/- BMMs even when MTOR inhibitors were present." (PMID 27942021, 2016). "Furthermore, MTOR hyperphosphorylation might trigger a counteracting mechanism to prevent autophagic digestion of parasites in the early infection phase." (PMID 26226952, 2015). "Moreover, downregulation of MTOR expression by transfection with specific siRNA prior to infection resulted in significantly decreased MTOR and p-MTOR levels as well as a decreased infection rate compared to L. m.-infected BMDM, which were transfected with negative control siRNA." (PMID 26226952, 2015). "Taken in sum, our current work strongly suggests that the use of mTOR dependent autophagy to study mycobacterial killing (and possibly other pathogen killing) is artificial and casts shadows on the endogenous host-pathogen biochemistry that naturally occurs during infection." (PMID 24528777, 2014). "However, mTOR inhibition within T cells could force them to differentiate into Treg/Th2 cells, which would likely perpetuate the infection." (PMID 23028309, 2012). "In hTCEpi cells, phosphorylated levels of mTOR, S6, and ULK1 were all decreased 2 hours post infection." (PMID 39791872, 2025). "Following infection with S. aureus, the activation of STAT3 occurs later than other signaling pathways, such as ERK and mTOR, leading to the delayed suppression of TFEB, a key regulator of lysosomal biogenesis and function." (PMID 40936092, 2025). "HuH-7 cells were transfected with the mTOR expression plasmid, either alone or co-transfected with RRM2 or control siRNA, followed by infection with DENV-2 at an MOI of 0.1." (PMID 41341853, 2025). "These dual-mode data underscore how infection stress couples the sulfur-redox system (GSH) and energy-sensing (mTOR) with lipid metabolism remodeling." (PMID 40806239, 2025). "Our experiment confirmed that Ad-VT infection in MCF-7 cells leads to altered phosphorylation of mTOR and S6K proteins, suggesting potential involvement of the mTOR/S6K signalling pathway in apoptin-induced apoptosis." (PMID 40453070, 2025). "Infection disrupts mitochondrial morphology and suppresses oxidative phosphorylation while activating the PI3K/Akt/mammalian target of rapamycin (mTOR) pathway to drive metabolic reprogramming, enhancing glycolysis to meet energy demands." (PMID 41427835, 2025). "The main suspected TMA trigger was drug toxicity, in patients on CNI therapy alone, combined CNI and mTOR inhibitor therapy, and CNI therapy plus an infection." (PMID 40735634, 2025). "It is worth noting that observed disruptions in mTOR expression following exposure to APEC, both in early and late stages, underscore the complex temporal dynamics of molecular responses to infection and treatment." (PMID 39721265, 2024). "Densitometry data clearly indicated that post-infection, there was a notable decrease in PDCD4 expression coupled with an increase in phosphorylated S6 (pS6) levels, indicative of mTOR pathway activation." (PMID 38912807, 2024). "The contribution of mTOR signalling to pathways leading to full CD8+ T-cell activation has been demonstrated in several immune contexts, including infection." (PMID 39114656, 2024).
infection (continued). "At the protein level, Infection with G. parasuis resulted in reduced p-PI3K, p-Akt and p-mTOR levels in the spleen compared to the control group (p < 0.01)." (PMID 38582846, 2024). "Inhibition by chemical means of mTOR signaling resulted in decreased NS3 viral protein expression and lower viral titers under all infection conditions." (PMID 37227282, 2023). "In contrast, in primary normal human astrocytes, inhibitors of PI3K, AKT, and mTOR, including wortmannin (PI3K), MK2206 (AKT), and rapamycin (mTOR), inhibit JCPyV infection while MAPK-ERK inhibitors like U0126 fail to reduce infection." (PMID 36786589, 2023). "Starting 24 h post infection, we found a simultaneous and significant decrease in PI3K and an increase phospho-mTOR (that subsequently decreased at 48 and 72 h p.i.)." (PMID 37026095, 2023). "The results indicated that ORFV infection activated autophagy by mediating the expression of upstream regulators (including TSC2, Rheb and P70S6K) of mTOR and thus inhibiting mTOR expression." (PMID 36918891, 2023). "Taken together, our results indicate that phosphorylation and subsequent inactivation of FOXO3a by T. gondii require live infection and occur in a PI3K-AKT-dependent fashion independently of EGFR, PKCα, and mTOR activity in HFF." (PMID 37387601, 2023). "The infection model group had significantly higher levels of LC3B, Beclin1, and p-mTOR than the control group." (PMID 37077346, 2023). "Transcription expression of mTOR and IGF1 increased at 6 h after infection, but gradually decreased after 12 h." (PMID 36423079, 2022). "Our data indicated that infection of lung tissue and DEF with either a highly virulent or avirulent H5N1 virus favored ubiquitinylation of Akt, mTOR, p70S6K, and rpS6." (PMID 36059479, 2022). "We concluded that M. bovis-infected bMECs alleviated cellular autophagy through a PI3K-Akt-mTOR pathway, and that PTEN acted as a protective gene regulating autophagy, a key step in controlling infection." (PMID 35958147, 2022). "It has been shown that prolonged treatment with PI3K-AKT-mechanistic target of rapamycin (mTOR) signaling pathway inhibitors markedly promote HBV copies in HBV replication and natural infection models." (PMID 35252042, 2022). "SARS-CoV-2 infected cells showed increased levels of mTOR, S6K1, and S6 phosphorylation by over 3-fold 24 hpi (hours post-infection) compared to the baseline levels of mock cells." (PMID 36661509, 2022). "Most of the mTOR inhibitors inhibit both AdV3 and AdV5 infection with similar EC50s, suggesting that PI3K/Akt/mTOR pathway is critical for adenovirus replication." (PMID 35632701, 2022). "Coronavirus also upregulates PI3K/AKT/mTOR signaling, and kinase inhibitors such as wortmannin (PI3K inhibitor), MK-2206 (AKT inhibitor) and rapamycin (mTOR inhibitor) restrains CoVs infection in vitro." (PMID 33920748, 2021). "Both infections induced metabolic response, and AKT/mTOR activation was terminated by leucine supplementation in addition to induction of the intrinsic apoptotic pathway in CBMo." (PMID 33924101, 2021). "HPV-mediated activation of the phosphatidylinositol 3-kinase (PI3K) and mammalian target of rapamycin (mTOR) pathway downstream of EGFR efficiently suppresses autophagy and enables infection." (PMID 34960729, 2021). "The increased expression of p-mTOR and p-AKT induced by infection was significantly suppressed by coincubation with rapamycin (1 μM, 8 h)." (PMID 34900761, 2021). "In summary, our results demonstrate that NLRP3 inhibited autophagy by binding to mTOR, while QFY reversed infection-impaired autophagy through down-regulation of NLRP3." (PMID 35111047, 2021). "IPEC-J2 cells were treated with mTOR specific activator-MHY1485 and inhibitor-RAPA, followed by infection with TGEV." (PMID 34367129, 2021). "Overall, our results suggest that pHIVNL4-3 infection enhanced T-cell activation, and increased the expression of ABC drug efflux transporters potentially through the mTOR signaling pathway." (PMID 34421607, 2021).
infection (continued). "Thus, SARS‐CoV‐2 infection could lead to a hyper‐activation of hepatic mTOR signalling, via direct infection of hepatic cells, or indirect, cytokine storm‐related systemic IL‐6‐dependent effects, which could contribute to the steatotic phenotype in livers of COVID‐19 patients." (PMID 33190346, 2021). "To explore the mechanisms underlying BTB damage induced by UPEC infection, we analyzed BTB integrity and the involvement of the mTOR-signaling pathway using in vivo and in vitro UPEC-infection models." (PMID 33679734, 2021). "It directly suppressed the NF-κB pathway and reversed the BEFV-activated Src/JNK pathway at the early stage of infection and reversed the BEFV-suppressed PI3K/Akt/mTOR pathway at the late stage of infection." (PMID 33329515, 2020). "Western blot validation of the downstream effector molecules of these pathways revealed a dose-dependent activation of Akt, mTOR, S6K1 and 4E-BP1 at 24 hours post infection (hpi)." (PMID 32691695, 2020). "Following infection of murine BMDMs with S. typhimurium, for example, targets AMPK, SIRT1, and LKB1 to lysosomes for degradation, thereby preventing inhibition of mTOR and activation of autophagy even though ATP and NAD+ are depleted." (PMID 31936570, 2020). "Specifically, the inhibition of mTOR has been found to suppress transcription of cellular receptors (i.e., CCR5) and the HIV-1 LTR during infection." (PMID 32823598, 2020). "Cell lysates, prepared 24 h after infection, were subjected to western blot analyses using antibodies specific for N-Ras, p-Akt, p-S6K1, p-mTOR and NP." (PMID 32326380, 2020). "Further work is required to fully define the effects of the mTOR pathway on T-bet activity and on the function of effector CD4+ T cells during infection." (PMID 32817333, 2020). "The results showed that the PI3K/Akt/mTOR pathway was inhibited by 2 h of E44 infection of HBMECs, and NT pretreatment significantly activated the PI3K/Akt/mTOR pathway." (PMID 33042863, 2020). "Collectively, these results show that aspirin reverses BEFV-mediated degradation of IκBα, upregulates PI3K/Akt/NF-κB and Src/JNK/AP1 pathways in the early stage of infection, and downregulates the PI3K/Akt/mTOR pathway in the late stage of infection." (PMID 33329515, 2020). "The expression and activation of TFEB were enhanced early under the infection of S. aureus, which was followed by shrinkage to weaken lysosomal functions due to the delayed activation of ERK, mTOR, and STAT3." (PMID 33324360, 2020). "Our previous study has revealed that HPV11 E6 induces autophagy by suppressing the AKT/mTOR and Erk/mTOR pathways, suggesting elevated autophagy level is beneficial for the survival of HPV11 in host cells after successful infection." (PMID 33197887, 2020). "Our studies have shown that deletion of HIF-1α or inhibition of mammalian target of rapamycin (mTOR; known to stabilize HIF-1α) attenuates MPLA-induced increased glycolysis, abolishing the protective effect of MPLA against infection." (PMID 33679711, 2020). "By stimulating mTOR, HIV-1 can use the inhibition of autophagy to diminish cross-presentation in infected human monocyte-derived DCs, which enables transfer of infection to neighboring cells such as CD4+ T cells from infected DCs." (PMID 31936570, 2020). "In this work, we report that BEFV induces autophagy via upregulation of the PI3K/Akt/NF-κB and Src/JNK/AP1 pathways in the early to middle stages of infection and suppresses the PI3K/Akt/mTOR pathway at the late stage of infection." (PMID 31601269, 2019). "This study demonstrates that E. granulosus (s.s.) infection and ES products, including EgTPx, can induce PM recruitment and alternative activation, at least in part, via the PI3K/AKT/mTOR pathway." (PMID 31727141, 2019). "Our results revealed that BEFV reduced the phosphorylated forms of mTOR and 4E-BP1 in the late stage of infection as compared to mock-treated cells." (PMID 31601269, 2019).
infection (continued). "Autophagy is initiated when stresses such as starvation and infection increase AMPK activity, which inactivates the mechanistic target of rapamycin complex (mTOR)." (PMID 31905741, 2019). "Again, blockade of mTOR signaling inhibits the development of the metabolic and functional macrophage phenotype and ablates MPLA-induced resistance to infection in vivo." (PMID 30994733, 2019). "The results of this study show that HVJ-E infection induces apoptosis in HeLa cells through the mitochondrial pathway, and that this induction is triggered by PI3K/Akt/mTOR/P70SK-mediated autophagy in an ERK-dependent manner." (PMID 30534001, 2018). "Conversely, HSVQ induces AKT/mTOR activity and PD-L1 expression, which diminishes the antitumor immune response observed with HSV-P10 infection." (PMID 30479334, 2018). "Helicobacter pylori can promote an inflammatory response during infection, which is regulated through c-Met/PI3K/Akt/mTOR signaling pathway activation." (PMID 29710817, 2018). "Histological analysis further revealed the activation of the mTOR signaling pathway, as indicated by the expression of p-mTOR and p-S6RP, which were predominant in both bronchiolar and alveolar epithelial cells after infection with pH1N1." (PMID 30422993, 2018). "In the current study, we investigated the efficacy of three different mTOR inhibitors, namely rapamycin, GSK-2126458 and KU-0063794, in a therapeutic setting during infection with L. major." (PMID 30133440, 2018). "We found that infection with DEV activated the metabolic regulator 5′ AMP-activated kinase (AMPK) and inhibited activity of mechanistic target of rapamycin (mTOR)." (PMID 29018776, 2017). "After retesting shRNAs targeting the top screen candidates, we found that infection with shRNAs targeting four of these genes (CDKN1A, MTOR, MYOT, and UBE2E1) resulted in a consistent bypass of OSKM-induced senescence." (PMID 29138277, 2017). "During the acute phase of infection, we observed an increased expression of GRAIL with low Otub-1 and mTOR expression and activation in CD4 T cells." (PMID 28114324, 2017). "Increased activation of mTOR and AKT are both known to result in the inhibition of autophagy, initiated at early time periods of infection." (PMID 28192515, 2017). "Conversely, rapamycin treatment reduced mTOR signaling and impaired IRF4 expression and CD8+ T cell differentiation, leading to impaired viral clearance and host recovery from infection." (PMID 27242787, 2016). "In those infections, host cell death was detected only in the presence of PP242 and thymidine, demonstrating that bacterial replication together with MTOR suppression are required for induction of host cell death." (PMID 27942021, 2016). "Migration from the lymph node to the site of infection is in part, due to downregulation of CD62L and CCR7, which is dependent on activated mTOR." (PMID 27242787, 2016). "Activation of mTOR signaling pathway by either leucine stimulation, Ad-S6K1 infection or TSC1 knockdown all reverses the inhibition effect of ghrelin on Th17 cells." (PMID 25658305, 2015). "Once HIV establishes a productive infection, Nef binds BECN1 resulting in MTOR activation, TFEB phosphorylation and cytosolic sequestration and the inhibition of autophagy." (PMID 26115100, 2015). "During permissive infection, Nef binds BECN1 resulting in mammalian target of rapamycin (MTOR) activation, TFEB phosphorylation and cytosolic sequestration, and the inhibition of autophagy." (PMID 26115100, 2015). "The specificity of genetic knockdowns of mTOR, Beclin-1 and Atg7 have confirmed that HPV-induced restraint of autophagy is important for early infection events." (PMID 25202355, 2014). "Notable examples are the virus-orchestrated activation of mTOR and MAP kinases, which promote translation during the lytic cycle and result in the expression of viral ORFs required for the progression of infection." (PMID 24453964, 2014).
infection (continued). "The IL-6, mTOR, CXCR4 and PI3K signaling pathways were the most significantly affected at 12 weeks post-infection." (PMID 23448601, 2013). "Although AMPK and mTOR have additional roles outside of cellular metabolism, here we focus on the effects of AMPK and mTOR on cellular metabolism during infection by intracellular pathogens." (PMID 24098109, 2013). "It has been demonstrated that blocking mTOR or its downstream signaling molecules impairs the production of type I interferon from plasmacytoid DCs; thus, preemptive activation of mTOR signaling in DCs could stop many infections before they get a chance to establish a foothold." (PMID 23028309, 2012). "Comprehensive analysis suggested that HS may enhance host immune responses to ST infection by coordinately activating multiple innate immune signaling pathways including the NLR, TLR, and mTOR signaling pathways." (PMID 40563970, 2025). "Considering the significance of the AMPK-mTOR pathway in regulating autophagy, we measured the effects of metformin on phosphorylated mTOR, a crucial autophagy pathway regulator, and SQSTM1, an autophagosome adapter and marker of autophagic flux, during SFTSV infection or rapamycin treatment." (PMID 40391966, 2025). "However, restoring the ATF4 level via Ad-ATF4 infection led to decreased levels of GPX4 and phosphorylated mTOR, S6, and 4EBP1 by erastin, suggesting that ATF4 mediates the erastin-induced mTOR inhibition and the subsequent activation of ferroptosis signaling." (PMID 40227255, 2025). "Furthermore, mTOR inhibitors such as RTB101, BEZ235, and RAD001, can upregulate IFN-induced antiviral immune responses and decrease infection rates in older adults." (PMID 41299782, 2025). "However, in the E. coli ∆VgrG2 infection group, we observed lower levels of LC3-II, suggesting that VgrG2 likely promotes autophagy in IPEC-J2 cells, potentially by influencing the mTOR signaling pathway and upregulating LC3-II expression." (PMID 40266908, 2025). "This catabolic process serves dual homeostatic and stress-responsive functions against oxidative injury, ischemia, and infection, governed by the PI3K-AKT1-mTOR signaling axis and core regulators (mTOR, Beclin-1, ATGs, AMPK)." (PMID 40777664, 2025). "While several studies have reported that CVB3 infection in HeLa cells induces autophagy by inhibiting mTOR, other reports found no significant alteration in mTOR activity following infection." (PMID 41471369, 2025). "We also investigated the impact of VgrG2 on the mTOR signaling pathway by examining the transcription levels of key genes, including mTOR, ULK1, Beclin-1, P62, LC3, Atg3, Atg5, and Atg12, following infection, and assessed the expression of the autophagy marker protein LC3-II." (PMID 40266908, 2025). "Few data are currently available on the appropriate management of this infection, and no specific therapy is known, often relying on the introduction of mTOR inhibitors for HHV‐8 infection and antivirals/immunomodulatory agents for managing KICS." (PMID 39731652, 2025). "In particular, these changes involved mTOR, BDNF, Akt, eEF2, CaMKI, and CREB-dependent signaling cascades in groups treated with monensin or enrofloxacin, and the fewest for doxycycline 15 days after infection." (PMID 39721265, 2024). "p-PI3K, p-Akt and p-mTOR protein expression was lower in the infection group than in the control group (P < 0.001), but their expression was greater in the levamisole, BMS-1 and 50–100 mg/kg baicalin groups than in the infection group (P < 0.05)." (PMID 39075562, 2024). "After infection, KSHV can binds to receptors on target cells to activate the PI3K/AKT/mTOR pathway." (PMID 38817860, 2024). "Interestingly, infection of the dHP CA1 region with the shGabrg2 virus induced molecular changes similar to those induced by ketamine administration, except for mTOR phosphorylation." (PMID 39218973, 2024).